MAGEE2 (MAGE family member E2)
Synonyms: HCA3
Tractability: PROTAC: its protein half-life has been measured.
Gene: Protein-coding gene on chromosome X (75,782,987 to 75,785,254, reverse strand). Ensembl gene ENSG00000186675.
Gene Ontology:
Molecular function: protein binding
Biological process: negative regulation of transcription by RNA polymerase II
Cellular component: nucleus
Homologues: Orthologues: chimpanzee MAGEE2 (98% identical), macaque MAGEE2 (95% identical), pig MAGEE2 (88% identical), dog MAGEE2 (87% identical), mouse Magee2 (84% identical), rat Magee2 (83% identical), rabbit MAGEE2 (61% identical), zebrafish ndnl2 (13% identical), Drosophila melanogaster MAGE (9% identical). Paralogues in human: MAGEE1 (26% identical), MAGEB18 (22% identical), MAGEB4 (22% identical), MAGEB1 (21% identical), MAGEB10 (21% identical), MAGED1 (20% identical), MAGEB2 (20% identical), MAGED2 (20% identical), MAGEB17 (20% identical), MAGEA10 (20% identical), MAGED4 (20% identical), MAGED4B (20% identical), and 25 more.
Diseases named in the same sentence as MAGEE2 in open-access papers:
MAGEE2 is named in the same sentence as 3 diseases in open-access papers, as found by Europe PMC text mining. Sharing a sentence is not in itself a finding about the gene and the disease. The quoted sentences say what the papers report.
breast carcinoma (1 paper, 2017). "Top HBF + BPA-dysregulated genes (ALDH1B1, ASTL, CA7, CPLX4, KCNV2, MAGEE2 and TUBA3E) are associated with poor overall survival in The Cancer Genomic Atlas (TCGA) human breast cancer cohort (n = 1082)." (PMID 28487351, 2017). "To gain clinical significance, using The Cancer Genomic Atlas (TCGA) breast cancer cohort, we dichotomized 1082 breast cancer subjects into two groups based on the expression of the seven genes (ALDH1B1, ASTL, CA7, CPLX4, KCNV2, MAGEE2 and TUBA3E)." (PMID 28487351, 2017). "We took advantage of the publicly available RNA-seq and survival data from TCGA and determined that seven differentially expressed genes (ALDH1B1, ASTL, CA7, CPLX4, KCNV2, MAGEE2 and TUBA3E) could be involved in breast cancer development, especially in Caucasian female patients with ER positivity." (PMID 28487351, 2017).
glioma (1 paper, 2020). A benign or malignant brain and spinal cord tumor that arises from glial cells (astrocytes, oligodendrocytes, ependymal cells). "This analysis revealed that some MAGEs including MAGED subfamily are overexpressed, while most others including MAGEE1, MAGEE2, MAGEL2, MAGEH1, NDN, and TRO are downregulated in glioma." (PMID 33425727, 2020).
MAGEE2 also shares sentences with these, for which no sentence is quoted: tumor (1 paper).